CD44 (CD44 molecule (IN blood group))
Diseases named in the same sentence as CD44 in open-access papers (continued):
Sharing a sentence is not in itself a finding about the gene and the disease.
cancer (continued). "Accumulating data demonstrates that CD44 is a cell surface marker of cancer stem cells and is of importance for the malignancy of GC cells." (PMID 32545648, 2020). "Analysis of TCGA (the Cancer Genome Atlas) datasets suggested that the level of LINC00963 was positively correlated with the expression of the cancer stemness markers (Sox2 and CD44) and drug resistance markers (ABCG2 and ABCB5)." (PMID 32357409, 2020). "Memory T cells (TM, CD4+/CD44+) are T cells that have had interaction with specific antigens or cancer, and are able to mount a strong and rapid response to the pathogen or cancer." (PMID 32372963, 2020). "Cancer stemness markers such as ALDH1/A2, CD44, CD166 and EpCAM are associated with drug resistance in cancers." (PMID 32899896, 2020). "6-Methoxymellein decreased the proportion of CD44+/CD24− MDA-MB-231 cancer cells from 80.3% to 41.6%." (PMID 32977636, 2020). "In this study, the biological evaluation of a redox-sensitive hyaluronic acid-based nanomedicine was intensively investigated on cancer cells with diverse expressed CD44 proteins." (PMID 31894722, 2020). "miR-383 was found to regulate the cancer stem cell properties of PCa cells via regulation of CD44, that in turn regulates their metastatic abilities." (PMID 33473254, 2020). "Expression levels of cancer stem cell markers (CD44, CD133, SOX2, OCT3/4, and NANOG) were also decreased after silencing of SKIL in CALU-3 and NCI-H520." (PMID 33268765, 2020). "There was an inverse correlation between the expression of XIST and cancer stem cell (CD44 + /CD24−) population." (PMID 32943985, 2020). "In the context of the discussion on how CD44 is acting in the development of cancer, the translocation of the protein into and out of the lipid raft domain appears to be a crucial factor." (PMID 32271757, 2020). "At 12 weeks, progenitor GSCs gave rise to tumors expressing mainly the progenitor marker ASCL1 and small populations of cancer cells expressing the neuronal marker DCX or the astro-mesenchymal marker CD44." (PMID 32641768, 2020). "HA-mediated uptake of NPs occurred in CD44high cells grown in adherent and 3D conditions thus demonstrating the capability to target also cancer stem-like cells in addition to differentiated cells overexpressing CD44." (PMID 31979218, 2020). "Significance of AR expression was correlated with prognostic biomarkers including cancer stem cell markers (CD44, CD24, and ALDH1), basal markers (CK5, CK14, and nestin), proliferation marker (ki-67), apoptotic marker (Bcl-2), and COX-2." (PMID 32850312, 2020). "As expected, increased mRNA expression of stemness genes was detected in ALDH+CD44+ cancer cells, compared with the ALDH−CD44− subset." (PMID 32390009, 2020). "Western blot assays showed that the decreased CDH1 expression and enhanced mesenchymal (CDH2 and vimentin) and cancer stemness (CD44, ABCG2, OCT4 and MYC) marker expression were abolished after treating MCF-7OE-UBE2O cells with rapamycin." (PMID 31907353, 2020). "In particular, nanoparticles decorated with targeting molecules on the surface have great potential to target cancer cells because cancer cells express many kinds of molecular receptors excessively such as CD44 and folate receptors." (PMID 32580439, 2020). "Although CD44 and IL-33/ST2 have been well documented in human cancer metastasis or prognosis, respectively, evidence of the CD44 gene SNPs combined with IL-33/ST2 pathway functional polymorphisms in HCC susceptibility and clinical characteristics is scarce." (PMID 33062675, 2020). "The identification of fibroblasts as drivers of cancer-specific CD44 expression profile and plasticity sheds light on the limitation of per se dynamic surface antigens as biomarkers." (PMID 32685007, 2020). "CD44, a cell surface adhesion marker expressed by cancer stem cells (CSC) has been reported as overexpressed in GC spheroids." (PMID 33003476, 2020).
cancer (continued). "As a transmembrane hyaluronic acid receptor and the most commonly used marker of CSCs, CD44 is recognized as a potential determinant against the ability of invasion and metastasis in cancer." (PMID 33071648, 2020). "Considering particular EMT/CSC molecular actors, studies, for instance, have detected CD44, often in conjunction with other canonical EMT markers, in CTCs isolated from many cancer types, which was associated with poor clinical outcomes in some studies." (PMID 32575608, 2020). "Stemness markers promote cancer stem cell-like formation, such as SOX2, Nanog, Oct-4, CD44, c-Myc, and KLF4, are linked to drug resistance." (PMID 33082357, 2020). "For instance, in 2016 a phase I study targeting CD44, a cancer cell progenitor marker of EAC, achieved a limited clinical benefit among AML patients." (PMID 32560537, 2020). "HA binding to CD44 promotes cancer cell migration through SRC-induced cortactin cytoskeleton function." (PMID 31898491, 2020). "To confirm that, here we performed a JNK or JAK2 inhibitor test by assessing the anti-cancer effects of pKAL on CD44, Oct 3/4, β-catenin, and MMP-9 as well as the STAT 3 activity of RT-R-MDA-MB-231 cells." (PMID 32326231, 2020). "HDAPPs for the current study were functionalized with hyaluronic acid in order to target the cancer stem cell marker CD44." (PMID 32328438, 2020). "CD44 contributes to the regulation of stemness, cell proliferation, and differentiation in stem/progenitor cells and cancer-propagating cells." (PMID 31901081, 2020). "Hyaluronic acid, a main component of the extracellular matrix, is a natural ligand to CD44 and has been used as a targeting moiety for CD44‐overexpressed cancers, facilitating preferential uptake and potent therapeutic efficacy." (PMID 32725633, 2020). "CTCs were identified as HLA+ (a human-specific marker), and CD44+CD24- cells indicate cancer stem cells." (PMID 33035223, 2020). "In a recent study, CD44 was identified as a key component in clustering of cancer cells both in patient-derived xenograft (PDX) models in mice and in metastatic breast cancer patients." (PMID 32984308, 2020). "In this regard, the number of CD133+CD54+CD44+ circulating cancer stem cells is present in the blood and is a biomarker of treatment selection and liver metastasis in patients with CRC." (PMID 32071283, 2020). "The ready-made minigene, FMv2, was modified to include the sequence of exon v8 of the CD44 gene because exon v8 skipping of the CD44 gene has been reported to be a possible therapy for cancer treatment." (PMID 33266296, 2020). "Among others, these changes results in the expression of CD44, which allows cells to invade more deeply the surrounding tissue and enhances the glycolytic phenotype of cancer cells that are exposed to hypoxia." (PMID 32024247, 2020). "Owing to the interaction between chondroitin sulfate and CD44 receptor, chondroitin sulfate has been utilized in DDS to target CD44 overexpressing cancer cells and promote receptor-mediated endocytosis." (PMID 32133350, 2020). "Second, although CD44 is expressed on these syngeneic cancer cells, CD44 is also expressed on activated immune cells." (PMID 32927646, 2020). "This is consistent with the fact that CD44, as major receptor HA, is abundantly expressed on cancer stem cells which facilitates targeting of toxic effects of H2O2 on cancer cells." (PMID 33456676, 2020). "The results showed that HA-mExo-Dox selectively delivers doxorubicin to CD44-overexpressing cancer cells and exerts enhanced antitumor activity." (PMID 33023062, 2020). "The CD44 is a multifunctional cell surface molecule involved in cancer cell proliferation and metastasis." (PMID 31621555, 2020). "For instance, a cluster of the differentiation protein CD44 shows high expression in cancer cells, and sodium hyaluronate can be used for surface modification of nanoparticles, and targeting CD44 in cancer cells." (PMID 33195038, 2020).
cancer (continued). "Aldehyde dehydrogenase activity (termed ALDH+) and CD44+/CD24− mark two largely non‐overlapping populations of cancer stem cells, which have epithelial‐like and mesenchymal‐like phenotypes, respectively." (PMID 32667137, 2020). "Numerous attempts have been made to identify HCC cells with stem cell properties enriched some cell surface phenotype, specially CD44 and Nanog as cancer stem cell markers." (PMID 32376896, 2020). "CD44, cell surface glycoprotein, is known mediator of signaling pathways modulating the response of cancer cells to cytotoxic stimuli." (PMID 32456134, 2020). "HAS2-AS1 is key in TGF-β- and HAS2-induced breast cancer EMT and cancer stemness as increased HAS2 secretes HA that promotes EMT via CD44." (PMID 33543032, 2020). "ATRA can enhance the cytotoxicity of low-dose cisplatin and 5-fluorouracil against CD44+ cancer stem cells." (PMID 32487125, 2020). "The nuclear distribution of CD44-ICD was magnified in cancer cells disseminating from the lumen [arrows]." (PMID 33062960, 2020). "EPHB3 expression was higher in CRCs than in normal mucosa and was associated with the intestinal stem cell markers EPHB2, OLFM4, LRIG1, and a proposed cancer stem cell marker, CD44." (PMID 32294981, 2020). "Aberrant glycosylation has been previously identified in various cancer related proteins, such as the glycoprotein CD44, which has been shown to be a major carrier of STn and associated to increased metastatic potential and poor survival in gastric cancer." (PMID 32081911, 2020). "CD44, the principle cell surface receptor for hyaluronan (HA), has been reported as a cancer stem cell signature in many cancers of hematopoietic and epithelial origins." (PMID 31898491, 2020). "As the key regulator of CD44, BRG1 is known to promote the expression of CD44 and play a crucial role in the invasion and migration of cancer cells." (PMID 33071648, 2020). "Anti-CD44 mAbs were also found to exhibit significant antitumor activity in mouse xenograft models of human cancers." (PMID 33000243, 2020). "Further investigation has elucidated a mechanistic role for CD44 in maintaining the cancer stem cell phenotype as well as in cancer invasion and metastasis." (PMID 32636398, 2020). "CD44 and RHAMM expression levels have been linked to the progression of several types of cancer and are known to mediate HA cellular singnaling." (PMID 32610620, 2020). "The overexpression of CD44 in this cancer is an early event during carcinogenesis initiation, which is responsible for the acquisition of a senescence-resistant phenotype and the accumulation of mutations by hepatocytes undergoing transformation." (PMID 33199679, 2020). "For example, Sam68 enhances the inclusion of variable exon 5 of CD44, promoting the migration of both cancer cells." (PMID 32106418, 2020). "qPCR analysis after 3, 7 and 14 days revealed considerably higher expressions of cancer stem cell-related gene CD44 in spheroids respect to adherent cells and this effect is enhanced in those generated in hanging drop with MC-enriched media." (PMID 32576846, 2020). "One of the multifunctional, protumoral factors of interest secreted from myofibroblasts and cancer-associated-fibroblasts (CAF), respectively, is IL-6 (e.g. 70,71), which indeed slightly enhanced the CD44 surface signal in LS1034 cell cultures." (PMID 32685007, 2020). "CD44 is known to co-localize with HER2 preventing the binding of the anti-HER2 cancer treatment trastuzumab through steric hinderance." (PMID 32774772, 2020). "CD44, a marker for cancer stem cells, is involved in many different cellular mechanisms; however, the different functional roles of CD44 standard and its isoforms are not fully understood." (PMID 31963309, 2020).
cancer (continued). "A high proportion of cancer cells coexpresses TF and CD44 as a marker of cancer-initiating or stem cells." (PMID 32280709, 2020). "Hyaluronic acid (HA), as a target component of CD-44 (cancer stem cell marker), is connected to Ag-GQDs through an EDC-NHS coupling reaction, so that the synthesized HA-Ag-GQDs-CMI can reach cancer cells accurately." (PMID 33008457, 2020). "The hyaluronic acid receptors CD44 and RHAMM are closely linked to cancer progression and dissemination." (PMID 33379400, 2020). "Markedly up-regulated IL6 after knocking-down of UBC9 activated the expression of CD44, which was a prominent marker of cancer stem cells." (PMID 33244139, 2020). "Analysis revealed that genes associated with cancer stem cells, such as POU5F1 (OCT4), SOX2, NANOG, BMI1, BMP2, CD44, SOX9, and ALDH1 were markedly upregulated in enzalutamide resistant cells." (PMID 33339129, 2020). "The CD44 molecule on the surface of cancer cells interacts with molecules in endothelial cells, resulting in termination of cell circulation within the blood as the cell reaches the target organ." (PMID 32209138, 2020). "Cancer stem cell marker CD44 was detected by immunofluorescence analysis of the cells derived from tumorspheres in all experimental conditions." (PMID 32899449, 2020). "Until now, the function of CD44 in cancers is not fully understood, although data have proved that CD44 activities are usually triggered by binding with its ligands, especially HA." (PMID 33292278, 2020). "The identification of upregulated CD44 was particularly interesting given CD44 is commonly used as a marker for stemness properties in cancer cells." (PMID 32829692, 2020). "ZEB1 has been proposed to be important for maintenance of the cancer stem cell (CSC) properties in the presumed CD133+/CD44+ cancer stem cell subpopulation in B16-F10 melanoma cells." (PMID 32796736, 2020). "In conclusion, this study suggests that pKAL exhibit anti-cancer effects on RT-R-MDA-MB-231 cells by suppressing CD44 and Oct 3/4, β-catenin and MMP-9, which appeared to be linked to RT resistance of RT-R-MDA-MB-231 cells." (PMID 32326231, 2020). "A decrease of the CD44-positive population was also observed in IL-17RB-knockdown cells, and downregulation of cancer stemness activity of IL-17RB-knockdown cells was also shown by the sphere formation assay." (PMID 33082357, 2020). "The modulator of Wnt signaling (ICG-001) enhanced the expression of microRNA-150 which acts as a negative regulator of CD44, resulting in the suppression of cancer cell migration." (PMID 33303029, 2020). "CD44 is a transmembrane glycoprotein that has been recognized as a CSC marker in a variety of cancers." (PMID 32158358, 2020). "As a CTC isolation tool, anti-CD44 antibodies have been used to capture CTCs from cancer patient blood." (PMID 32984308, 2020). "The prepared probes exhibited low phototoxicity and enabled three-dimensional (3D) darkfield imaging with localization and spectroscopic identification of fixed CD44-expressing cancer cells." (PMID 32722426, 2020). "Subsequently, we also observed that CD34-overexpressing PKP+ cancer cells increased p-AKT, p-STAT3, and CD44 cancer stemness protein expression, but reduced p-AMPK protein levels according to Western blot analysis." (PMID 32586050, 2020). "CD44, a receptor for hyaluronic acid, is overexpressed in some types of cancer such as pancreatic, lung, ovarian, and breast cancer." (PMID 33023062, 2020). "Alternative splicing of the 9 variable exons of human CD44 pre-mRNA produces various mRNAs that are involved in different aspects of cancer progression and development." (PMID 33143085, 2020). "We found CD44 to be significantly differentially expressed between the cancer cells and epithelial cells (p value 1.89E-13) and between the cancer cells and redirected cells (p value 1.53E-13)." (PMID 32774772, 2020).
cancer (continued). "Gli1, LSD1, Sox9 were primarily expressed in the nucleus of cancer cells; CD44 primarily located in the membranes of cancer cells." (PMID 32430068, 2020). "Collectively, these data suggest that survival and outgrowth of CD44+ cancer stem cells are dependent on continued HA synthesis through HAS2 activity." (PMID 32774770, 2020). "After knockdown/out of the HA receptor CD44 in cancer cells by shRNA and CRISPR/Cas9, the mechanism was investigated in vivo through intratibial inoculation and in vitro by coculture with HS5 cells." (PMID 32517712, 2020). "Further, the downregulation of the expression of miR-29 enhances the expansion of CK5+ and CD44+ cancer cells, resulting in increased stem-like properties in vitro and in vivo." (PMID 33014829, 2020). "Actually, we checked several cancer cell lines on the expression of CD44 and CD133, including HeLa cells and A549 cells." (PMID 32849878, 2020). "It is well known that ERM complex (Ezrin, Radixin and Moesin) are cytoskeletal molecules connected to CD44 C-terminal domain and are believed to be closely related to cancer malignancy." (PMID 33292278, 2020). "Studies on CD44 expression have been identified in various cancers, such as ovarian cancer, breast cancer, and oral cancer etc." (PMID 32434417, 2020). "Cyclodipeptides increased SNAIL levels and decreased levels of the hyaluronan receptor CD44, a cell surface adhesion receptor that is highly expressed in many cancers and regulates metastasis by alternative splicing and recruitment of CD44 to the cell surface." (PMID 32793477, 2020). "CD44 is involved in cell adhesion, migration and a range of pathophysiological processes as inflammation, wound healing and cancer." (PMID 33003440, 2020). "CD44, relevant in treatment resistance, has been proven to be a cancer stem cell surface marker of BCa." (PMID 32850423, 2020). "Previous studies have demonstrated that RA in combination with cisplatin showed a synergistic effect in decreasing cell viability in CD44(+) cancer stem cells." (PMID 32719599, 2020). "ALDH+CD44+ cancer cells transfected with siPDK4 exhibited lower expression of OCT4, KLF4, and BMI1 genes at both mRNA and protein levels." (PMID 32390009, 2020). "HA/CS NPs were loaded with a challenging water-insoluble drug, Everolimus (EVE), an antiproliferative agent currently approved by many agencies for treatment of advanced cancers, most of them characterized by CD44-overexpressing feature." (PMID 32183027, 2020). "For example, NANOG is enriched in CD133+ or CD44+ cancer cells as compared to CD133- or CD44- cells 60-62." (PMID 32754274, 2020). "Cancer cells utilized here showed positivity for CD44, ALDH1A1, and CK19 markers when grown on vasculature platform." (PMID 32155897, 2020). "In prostate cancer, transcriptional coactivator staphylococcal nuclease and tudor domain containing 1 (SND1) promotes the recruitment of Sam68 onto CD44 pre-mRNA, suggesting the significance of transcription-coupled RNA splicing events in cancer." (PMID 32106418, 2020). "The result showed that Gli1 related with cancer stemness proteins, CD44, LSD1, and Sox9 (all P < 0.05)." (PMID 32430068, 2020). "Here, HDAPPS were functionalized with hyaluronic acid (HA) to improve their binding specificity to CT26 mouse CRC cells using HA to target the cancer stem cell marker CD44." (PMID 32328438, 2020). "CD44 is a cell adhesion molecule and this trans-membrane glycoprotein increases the proliferation and metastasis of cancer cells by binding to hyaluronic acid." (PMID 32545648, 2020). "In this review, we focus on current data relevant to CD44, and outline CD44 structure, the regulation of CD44, functional properties of CD44 in carcinogenesis and cancer progression as well as the potential CD44-targeting therapy for cancer management." (PMID 33303029, 2020).